KRT26 (keratin 26)
Synonyms: K25B; K26; KRT25B; CK26; K25IRS2
Tractability: No criterion of Open Targets' tractability assessment is met for any kind of drug.
Gene: Protein-coding gene on chromosome 17 (40,766,238 to 40,772,201, reverse strand). Ensembl gene ENSG00000186393.
Pathways (Reactome):
Developmental Biology: Formation of the cornified envelope; Keratinization
Gene Ontology:
Molecular function: protein binding; structural constituent of skin epidermis; structural molecule activity
Biological process: epithelial cell differentiation; intermediate filament organization; morphogenesis of an epithelium
Cellular component: extracellular exosome; cytoskeleton; cytosol; keratin filament
Genetic constraint (gnomAD): Loss-of-function variants: 37 observed, 39.32 expected, observed/expected ratio (o/e) 0.94, 90% interval 0.72 to 1.24. The upper end of that interval is the gene's LOEUF score, 1.24, which puts it in group 5 of 6, group 1 being the genes least tolerant of losing a copy. Missense variants: 485 observed, 491.13 expected, observed/expected ratio (o/e) 0.99, 90% interval 0.92 to 1.07. Synonymous variants: 163 observed, 188.01 expected, observed/expected ratio (o/e) 0.87, 90% interval 0.76 to 0.99.
Homologues: Orthologues: chimpanzee KRT26 (99% identical), macaque KRT26 (94% identical), dog KRT26 (81% identical), mouse Krt26 (77% identical), pig KRT26 (76% identical), rabbit KRT26 (76% identical), rat Krt26 (75% identical), guinea pig KRT26 (66% identical). Paralogues in human: KRT27 (72% identical), KRT25 (68% identical), KRT28 (68% identical), KRT10 (55% identical), KRT24 (50% identical), KRT12 (48% identical), KRT14 (48% identical), KRT16 (47% identical), KRT15 (46% identical), KRT17 (45% identical), KRT13 (44% identical), KRT9 (41% identical), and 56 more.